DIRC3 (disrupted in renal carcinoma 3)
Synonyms: FLJ14199
Gene: Long non-coding RNA gene on chromosome 2 (217,284,019 to 217,756,656, reverse strand). Ensembl gene ENSG00000231672.
Diseases named in the same sentence as DIRC3 in open-access papers:
DIRC3 is named in the same sentence as 26 diseases in open-access papers, as found by Europe PMC text mining. Sharing a sentence is not in itself a finding about the gene and the disease. The quoted sentences say what the papers report.
melanoma (16 papers, 2019 to 2025). A malignant, usually aggressive tumor composed of atypical, neoplastic melanocytes. "Loss of DIRC3 through CRISPR interference markedly enhances anchorage-independent growth in a number of melanoma cell lines, which indicates metastatic potential." (PMID 41463281, 2025). "DIRC3 is down-regulated in melanomas and its lower expression level is associated with shorter survival." (PMID 33860799, 2021). "As anchorage-independent growth is a good predictor of melanoma metastasis in vivo, we assayed the effect of DIRC3 loss-of-function on growth in soft agar." (PMID 31881017, 2019). "We then assessed the generality of DIRC3-mediated control of anchorage-independent growth and extended our loss-of-function analysis to include additional DIRC3 expressing melanoma cell lines." (PMID 31881017, 2019). "DIRC3 depletion in human melanoma cells leads to increased anchorage-independent growth, a hallmark of malignant transformation, whilst melanoma patients classified by low DIRC3 expression have decreased survival." (PMID 31881017, 2019). "We next used CRISPRi to generate DIRC3 loss-of-function cell lines and investigate the role of DIRC3 in controlling cellular transformation in melanoma." (PMID 31881017, 2019). "DIRC3 therefore possesses IGFBP5–dependent gene regulatory functions in melanoma that act to control cancer associated biological processes." (PMID 31881017, 2019). "Importantly, downregulation of DIRC3 is strongly associated with poor prognosis and decreased overall survival in patients with melanoma." (PMID 41463281, 2025). "Disrupted in Renal Carcinoma 3 (DIRC3) lncRNA is transcriptionally repressed by microphthalmia-associated transcription factor (MITF)- SRY-box transcription factor 10 (SOX10) pathway in melanoma." (PMID 34638331, 2021). "Indeed, our results show that IGFBP5 depletion phenocopies the increased anchorage-independent growth effect of DIRC3 loss in SK-MEL-28 cells whilst others have reported that IGFBP5 overexpression reduces anchorage-independent growth in A375 melanoma cells." (PMID 31881017, 2019). "DIRC3 thus represents an exemplar to test whether MITF-SOX10 bound lncRNAs can modulate the downstream MITF-SOX10 transcriptional response in melanoma by regulating the association of these transcription factors with their binding sites in chromatin." (PMID 31881017, 2019). "DIRC3 is a MITF-repressed lncRNA that blocks the anchorage-independent growth of melanoma cells whilst the MITF activated lncRNA LENOX promotes melanoma cell survival and resistance to MAP kinase inhibitors." (PMID 41336739, 2025). "The role of DIRC3 in tumour suppression in melanoma is based on the modulation of transcriptional networks governed by MITF and SOX10." (PMID 41463281, 2025). "The authors identified 245 candidate lncRNAs associated with melanoma whose loci are jointly bound by MITF and SOX10, suggesting that DIRC3 exerts broad tumour-suppressive effects through IGFBP5-dependent mechanisms." (PMID 41463281, 2025). "Further investigation has uncovered that DIRC3 hinders the growth of melanoma cells by increasing the expression of the IGFBP5 gene, acting as a tumor suppressor." (PMID 39553554, 2024). "In their study, DIRC3 levels positively correlated with IGFBP5 in melanoma RNA sequencing samples and they discovered that DIRC3 acts in cis to control expression of IGFBP5." (PMID 36043126, 2022). "In a recent study, DIRC3 was found to act as a tumor suppressor, blocking the growth of human melanoma, and patients with high levels of DIRC3 showed significantly improved survival rates compared to those with low level." (PMID 36581632, 2022). "In melanoma cells, where DIRC3 is highly expressed, DIRC3 increases IGFBP5 transcription by preventing the TFs SRY-Box transcription factor 10 (Sox10) and melanocyte inducing transcription factor (MITF) from inhibiting IGFBP5 transcription." (PMID 36093095, 2022).
melanoma (continued). "Further study reveals that DIRC3 inhibits proliferation of melanoma cells via elevating the expression of tumor suppressor IGFBP5." (PMID 33860799, 2021). "In a screen for lncRNAs targeted by the melanoma transcription factors MITF and SOX10, DIRC3 was identified as a top hit and characterized as a melanoma tumor suppressor." (PMID 33329688, 2020). "We next performed RNA-seq of DIRC3 knockdown SK-MEL-28 cells to define the genome-wide impact of DIRC3 expression in melanoma." (PMID 31881017, 2019). "Our finding that DIRC3 is transcriptionally repressed by MITF-SOX10 is therefore consistent with TCGA data showing that DIRC3 levels correlate with an invasiveness gene expression signature in melanoma." (PMID 31881017, 2019). "Although, TAD structures can vary between normal tissues and cancers, a high proportion of TADs are invariable and we found that DIRC3 levels positively correlate with IGFBP5 in TCGA melanoma RNA-seq samples." (PMID 31881017, 2019). "This was based on the following reasons: (i) The Cancer Genome Atlas (TCGA) melanoma patients expressing low levels of DIRC3 show statistically significant decreased survival compared to those classified based on high DIRC3." (PMID 31881017, 2019). "(iii) DIRC3 levels positively correlate with an invasiveness gene expression signature across the 471 TCGA melanoma RNA-seq samples." (PMID 31881017, 2019). "Analysis of chromatin modification and MITF-SOX10 binding profiles showed that the DIRC3 locus contains three sites of MITF-SOX10 co-occupancy in melanoma: one upstream of the DIRC3 TSS (BS1) and two within the DIRC3 gene body (BS3-BS4)." (PMID 31881017, 2019). "Given the key role of IGFBP5 in melanoma biology, its regulation by DIRC3 downstream from MITF-SOX10 is likely significant." (PMID 31881017, 2019). "Taken together, these results define DIRC3 as a new melanoma tumour suppressor gene that acts through IGFBP5 to inhibit the anchorage-independent growth of melanoma cells in culture." (PMID 31881017, 2019). "A correlation exists between reduced DIRC3 expression in melanomas and decreased overall survival." (PMID 39553554, 2024). "MITF and SOX10 suppress expression of DIRC3, which potentially contributes to melanoma development." (PMID 33329688, 2020). "Moreover, it was observed that DIRC3 depletion induces an increased SOX10 (SRY-box transcription factor 10) repression of IGFBP5 in melanoma cell cultures, corroborating the tumor suppressor role of DIRC3." (PMID 33218058, 2020). "Together, these data indicate that DIRC3 is a nuclear localised transcriptional regulator that acts in cis in a transcript-dependent manner to activate expression of the adjacent IGFBP5 tumour suppressor gene in melanoma." (PMID 31881017, 2019). "Our results suggest that lncRNA components of MITF-SOX10 networks represent an important new class of melanoma regulators and predict that up-regulation of DIRC3 expression may represent an exciting new therapeutic strategy for melanoma." (PMID 31881017, 2019). "DIRC3 therefore appears to act through IGFBP5 to exert its tumour suppressive effect in melanoma." (PMID 31881017, 2019). "We show that one of these, DIRC3, may be a clinically important MITF-SOX10 regulated melanoma tumour suppressor that acts to block the spread of the disease and that melanoma patients with low DIRC3 expression have decreased survival." (PMID 31881017, 2019). "Together, these data provide strong initial evidence that DIRC3 may act as a clinically important new lncRNA regulator of melanoma." (PMID 31881017, 2019). "Although we can’t rule out the possibility that DIRC3 also regulates IGFBP5 independently of SOX10, our results are consistent with a model in which DIRC3 acts locally to block SOX10 chromatin binding at melanoma regulatory elements and activate IGFBP5 expression." (PMID 31881017, 2019).
melanoma (continued). "To illustrate proof of concept that some MITF-SOX10 bound lncRNAs may comprise an important new class of melanoma regulators we prioritised DIRC3, a multi-exonic 3,384 nucleotide transcript in human melanoma cells, for further investigation." (PMID 31881017, 2019). "In particular, our data indicates that DIRC3 may be a novel clinically important melanoma tumour suppressor gene and we predict that driving up-regulation of DIRC3 expression may represent a new therapeutic strategy for melanoma." (PMID 31881017, 2019). "This indicates that DIRC3 regulation of anchorage-independent growth in melanoma is cell line-independent and is in agreement with TCGA clinical data showing that melanoma patients expressing low levels of DIRC3 display decreased survival, compared to those classified based on high DIRC3 expression." (PMID 31881017, 2019). "The results showed that CRISPRi mediated stable depletion of DIRC3 in A375 and 501mel melanoma cells, using either DIRC3sg1 or DIRC3sg2 to target dCas9-KRAB to the DIRC3 promoter, also resulted in significantly increased colony formation in soft agar compared to control." (PMID 31881017, 2019). "Subcellular fractionation experiments first showed that DIRC3 is a nuclear-enriched transcript in human melanoma cells suggesting that it may function as a novel transcriptional regulatory lncRNA." (PMID 31881017, 2019). "Therapeutic upregulation of DIRC3 may therefore represent a promising strategy for melanoma." (PMID 41463281, 2025). "Therefore, DIRC3 may have dual roles at different stages of the disease and down-regulation of DIRC3 tumor suppressor function in metastatic melanomas may be an important event in melanoma progression." (PMID 34638331, 2021). "The functional role of DIRC3 lncRNA is likely to be that of tumor suppressor, and its relevance to thyroid cancer and other human malignancies such as, originally, familial renal cancer, melanoma, breast cancer and laryngeal squamous cell carcinoma has been reported." (PMID 33551988, 2020). "DIRC3 is upregulated in melanoma and may be used as an inhibitor of melanoma." (PMID 33381546, 2020). "This suggests that DIRC3 may have dual roles at different stages of the disease and that down-regulation of DIRC3 tumour suppressor function in metastatic melanomas may be an important event in melanoma progression." (PMID 31881017, 2019). "Among these, the authors identified and characterized a novel lncRNA and DIRC3, expressed in melanocytes and silenced in proliferating MITF-SOX10 high-expressing melanomas." (PMID 35159386, 2022). "DIRC3 acts in cis as an epigenetic regulator of IGFBP5 gene expression and inhibits invasion and migration of melanoma cells." (PMID 35159386, 2022). "Since DIRC3 expression is negatively correlated with both MITF and SOX10 levels, its expression increases in invasive MITFlow melanoma cells." (PMID 34638331, 2021). "Of note, MITF, with which SAMMSON is co-amplified at 3p13-3p14, is a transcriptional regulator of lncRNA DIRC3, which is disrupted by balanced translocations in renal carcinoma and suppressed by SOX10 in melanoma cells (see Translocations)." (PMID 33329688, 2020). "Taken together, these data provide strong evidence that DIRC3 is transcriptionally repressed by SOX10 and MITF in melanoma." (PMID 31881017, 2019). "We propose that MITF-SOX10 bound lncRNAs, such as DIRC3, which function using this mechanism of action have potential to modify the MITF-SOX10 transcriptional response in melanoma." (PMID 31881017, 2019). "We found that stable reduction of DIRC3 expression, using different dCas9-KRAB targeting sgRNAs, led to a significant increase in melanoma cell colony formation in soft agar." (PMID 31881017, 2019). "Our work highlights that MITF-SOX10 bound lncRNAs, as exemplified by DIRC3, can function as important downstream components and feedback regulators of MITF-SOX10 expression networks in the control melanoma growth and progression." (PMID 31881017, 2019).
melanoma (continued). "Collectively these data are consistent with low MITF-SOX10 increasing DIRC3 expression in invasive primary melanomas, but then at a site of metastatic colonization reestablishment of MITF-SOX10 would suppress DIRC3 expression to allow proliferation to occur." (PMID 31881017, 2019). "To test if DIRC3 is a MITF and SOX10 regulated target gene we first used multiple different siRNAs to deplete these two transcription factors in 501mel, SK-MEL-28 and A375 human melanoma cell lines, and measured changes in DIRC3 expression using RT-qPCR." (PMID 31881017, 2019). "We show that one of these, Disrupted In Renal Carcinoma 3 (DIRC3), may be a clinically important MITF-SOX10 repressed melanoma tumour suppressor gene that inhibits anchorage-independent growth." (PMID 31881017, 2019). "DIRC3 acts in cis and modifies chromatin structure and suppresses SOX10 binding to the promoter of neighboring insulin-like growth factor binding protein 5 (IGFBP5) gene, which activates this tumor suppressor and inhibits anchorage-independent melanoma cell growth." (PMID 34638331, 2021).
thyroid cancer (11 papers, 2016 to 2024). "GC haplotypic structure of rs16857609‐rs11693806 variants on DIRC3 gene is associated with breast and thyroid cancers in European population." (PMID 39031745, 2024). "In a GWAS study involving 561 Icelandic thyroid cancer cases and 40,013 controls, rs966423 variant of the DIRC3 was found to be associated with thyroid cancer risk and levels of thyroid-stimulating hormone for the first time." (PMID 38571492, 2024). "In a GWAS with 561 Icelandic individuals with thyroid cancer cases and 40,013 controls, DIRC3 variants were associated both with thyroid cancer risk and thyroid stimulating hormone levels." (PMID 35255942, 2022). "Several diseases have been associated with DIRC3, including renal cell, breast, and thyroid carcinoma." (PMID 35255942, 2022). "In an Italian study, the cumulative risk of 11 SNPs, including DIRC3, increased thyroid cancer risk." (PMID 33805984, 2021). "This study confirmed the association of 9q22.33 and 14q13.33 and led to the identification of a novel association to thyroid cancer for the SNP rs966423, located in the DIRC3 gene mapping to the 2q35 locus." (PMID 33946592, 2021). "Given that the association between rs966423 on the DIRC3 region and thyroid cancer was first reported in a European GWAS10 and was replicated in limited ethnic groups, it is impossible to ignore the possibility of the presence of population heterogeneity." (PMID 28703219, 2017). "In a genome-wide association study, DIRC3 was associated both with thyroid cancer risk and thyroid stimulating hormone level." (PMID 27793000, 2016). "In addition, the association between other DIRC3 variants with breast and thyroid cancer were investigated in a previous study." (PMID 39031745, 2024). "Our study also shows that DIRC3 rs6759952 is positively associated with thyroid cancer, and DIRC3 rs6759952 polymorphism may reduce TSH to elevate the thyroid hormone, contributing to promoting thyroid tumorigenesis." (PMID 33805984, 2021). "It is noteworthy that the last study showed novel loci containing genes that were previously implicated in thyroid cancer (e.g., HES1, SPATA13, DIRC3, ID4) and a positive association of TSH with VEGFA expression, therefore angiogenesis." (PMID 39767631, 2024). "Regarding genetic impacts, disruption in renal carcinoma 3 (DIRC3) is involved in thyroid cancer’s pathogenesis in various countries, including Korea." (PMID 33805984, 2021). "It is thus possible that DIRC3 changes alter thyroid stimulating hormone production and, indirectly, promote thyroid cancer development as a result of decreased thyroid epithelium differentiation." (PMID 27793000, 2016). "The present study suggested that DIRC3, GAP43, and LRP1B are involved in tumor suppressor activity to inhibit thyroid tumorigenesis, and their mutation may reduce the suppression of thyroid cancer risk." (PMID 33805984, 2021). "The results of gene expression showed that DIRC3 gene expression is significantly different from adjacent normal tissues in breast and thyroid cancer." (PMID 39031745, 2024). "DIRC3 is presumed to have tumor suppressor activity, as it is involved in the production of TSH, a primary factor of thyroid cell growth and function, and indirectly reduces the differentiation of thyroid epithelium, thus promoting thyroid cancer development." (PMID 33805984, 2021).
breast carcinoma (4 papers, 2019 to 2024). "Diseases associated with DIRC3 include renal cell carcinoma, breast cancer, and skin cancer." (PMID 36581632, 2022). "For example, regulatory elements within the 2q35 breast cancer susceptibility locus loop onto both IGFBP5 and DIRC3 whilst copy number alterations encompassing an IGFBP5 enhancer on 2q35 modulate breast cancer risk." (PMID 31881017, 2019).
Papillary Thyroid Cancer (3 papers, 2019 to 2020). "Moreover, we discuss whether the genetic polymorphism rs966423 in DIRC3 has any potential as a prognostic factor of papillary thyroid cancer." (PMID 31247975, 2019).
carpal tunnel syndrome (2 papers, 2022 to 2026). Entrapment of the median nerve in the wrist that is characterized by numbness, tingling and painful movement. "In this GWAS, the DIRC3 locus on chromosome 2 was significantly associated with both carpal tunnel syndrome and trigger finger, possibly explaining their co-occurrence." (PMID 36043126, 2022). "We leveraged the results of this GWAS to identify a single locus (DIRC3) that is significantly associated with both trigger finger and carpal tunnel syndrome." (PMID 36043126, 2022). "Next, we analysed the association of rs62175241 on DIRC3 and IGFBP5 expression in diseased tenosynovium samples from patients with carpal tunnel syndrome (n=77)." (PMID 36043126, 2022). "Although we were able to replicate our co-localised DIRC3 locus in patients with trigger finger and patients with carpal tunnel syndrome from the FinnGen cohort, we were unable to replicate all five trigger finger loci." (PMID 36043126, 2022). "We leveraged the co-localisation analysis between the traits for carpal tunnel syndrome and trigger finger to fine-map the DIRC3 locus by extracting the 95% credible set (n=21) of co-localised variants (appendix pp 8–9)." (PMID 36043126, 2022). "Regardless, these validation data strongly support a role for the DIRC3 locus in both trigger finger and carpal tunnel syndrome." (PMID 36043126, 2022). "These included associations with genes involved in neurotransmitter signaling (HTR3A), immune function (HLA-DQB1, BCL11A), extracellular matrix remodeling (COL11A1, ADAMTS17, LOXL4), axon guidance and neural development (DCC, ETV1, NEGR1), and carpal tunnel syndrome (DIRC3)." (PMID 41518141, 2026). "GWAS for trigger finger identified five independent loci, including one locus, DIRC3, that was co-localised with carpal tunnel syndrome and could be fine-mapped to rs62175241 (0·76, 0·68–0·84; p=5·03 × 10−13)." (PMID 36043126, 2022).
differentiated thyroid carcinoma (2 papers, 2020). Differentiated thyroid carcinoma (DTC), also known as papillary or follicular thyroid carcinoma, is a slow-growing malignancy usually presenting in adults as an asymptomatic thyroid mass. "We therefore evaluated the impact of the rs966423 polymorphism in the DIRC3 gene, including its relationship with unfavorable histopathological and clinical features and mortality, in differentiated thyroid cancer (DTC)." (PMID 32059462, 2020).
lung carcinoma (2 papers, 2022 to 2024). "Among the downregulated and hypermethylated genes associated with both RMST and DIRC3 (including BNIPL, HORMAD2, and NPHP3), HORMAD2 is the only gene related to lung cancer." (PMID 35356464, 2022).